RXRA (retinoid X receptor alpha)
Diseases named in the same sentence as RXRA in open-access papers (continued):
Sharing a sentence is not in itself a finding about the gene and the disease.
acute kidney injury (1 paper, 2022). Sudden and sustained deterioration of the kidney function characterized by decreased glomerular filtration rate, increased serum creatinine or oliguria. "Together, our findings elucidate a chromatin-mediated mechanism underlying differential responses of TECs to varying injuries and identify RXRα as a therapeutic target of acute kidney injury." (PMID 36443310, 2022).
adenovirus infection (1 paper, 2008). "Additional studies assessing the level of SHP in the liver during adenovirus infection, distribution patterns and phosphorylation status of PXR and RXRα in vitro and in vivo will further support these hypotheses and are currently underway in our laboratory." (PMID 18826641, 2008).
alcoholic liver diseases (1 paper, 2009). A disorder caused by damage to the liver parenchyma due to alcohol consumption. "More insights on RXR specific role in alcoholic liver disease come from experiments with animal models mainly from the group of Professor Wan JY that demonstrated an altered ethanol methabolism in RXRα null mice." (PMID 19756185, 2009). "In the last years there has been an increasing interest in the role of RXR, especially RXRα in alcoholic liver disease." (PMID 19756185, 2009).
autoimmune (1 paper, 2019). "Interestingly, RXRA-mediated signaling enhances differentiation of functionally competent CD4+ regulatory T cells and potently inhibits the formation of CD4+ T helper 17 cells, the latter of which have been strongly implicated in various autoimmune pathologies, including MS." (PMID 31023360, 2019).
Brain atrophy (1 paper, 2021). Partial or complete wasting (loss) of brain tissue that was once present. "Mice lacking RXRα in myeloid phagocytes (Mac-RXRα−/−) had a worse functional recovery and they developed brain atrophy after tMCAO." (PMID 34830207, 2021).
breast tumours (1 paper, 2020). "RXRA (-1.04 fold change) was also under expressed in breast tumours as compared to normal samples, consistent with analyses by Oncomine database." (PMID 32577155, 2020).
congenital heart disease (1 paper, 2016). "We also found that the interaction of RXRα with NKX2-5 mutations found in congenital heart disease (Q187H, R189G and R190H) was altered." (PMID 27683156, 2016). "Furthermore, we found that interactions between RXRα and a subset of NKX2-5 mutations causative for congenital heart disease (Q187H, R189G and R190H) were altered, linking TF–TF interaction networks to heart disease." (PMID 27683156, 2016).
dengue (1 paper, 2017). "We confirmed from the expression data on Thai dengue patients that only RXRA has statistically significant altered expression, supporting several lines of evidence linking retinoid receptors with infectious diseases and dengue." (PMID 28241052, 2017). "The genomic and functional confirmation of the protection conferred by OSBPL10, RXRA and related lipid metabolism against dengue illness supported in this study points out potential therapeutic applications." (PMID 28241052, 2017). "Even the immune system genes associated with dengue illness, such as TNF-α, IL-10, TGF-β1, FcγRIIa and CD209, can also be related with the RXRA gene in several pathways, as their expression is controlled by dimers formed by RXRA and other nuclear factors." (PMID 28241052, 2017). "RXRA forms heterodimers with VDR, previously identified as dengue protective in Vietnamese." (PMID 28241052, 2017).
dermatitis (1 paper, 2013). An inflammatory process affecting the skin. "Parallel to ATRA skin content, elevated mRNA levels of RARγ and RXRα, both the most abundant retinoid receptors in skin, were evidenced only in allergen-induced dermatitis." (PMID 23977003, 2013).
dry eye (1 paper, 2022). "Mice with loss of function mutation in the RXRα nuclear receptor have been reported to develop dry eye." (PMID 35402439, 2022). "Taken together these data show that reduced RXRα signaling enhances migration of γδT cells to the conjunctiva in dry eye and that IL-17 produced by these cells causes corneal and conjunctival epithelial disease." (PMID 35402439, 2022). "The purpose of this study is to investigate the mechanism for dry eye development in the RXRα loss of function mutant mouse." (PMID 35402439, 2022). "The greatest differences are seen in neutrophils, myeloid (macrophage and monocyte) and cDC2 cells and include IL-6, LPS-stimulated MAPK, NFkB, IL-17, and PPARα/RXRα signaling pathways that contain mediators relevant to dry eye pathogenesis." (PMID 35402439, 2022).
ductal carcinoma (1 paper, 2020). "However, RXRA (p = 0.007, fold change = 1.552) was only highly expressed in mixed lobular and ductal carcinoma tumours." (PMID 32577155, 2020).
enteritis (1 paper, 2025). Inflammation of the small intestine. "PUFA-induced RXRα activity in Paneth cells governed chronic transmural enteritis by enabling the expression of CXCL1." (PMID 41365295, 2025). "Collectively, we identify RXRα in Paneth cells as a metabolic stress sensor that enables enteritis, providing novel perspectives for the prevention and treatment of CD." (PMID 41365295, 2025).
eosinophilia (1 paper, 2010). "Postnatal skin-specific inactivation of both RXRα and RXRβ (RXRs) leads to the development of an AD-like disease characterized by partial hair loss, Th2 inflammation, eosinophilia, elevated TSLP epidermal secretion, and high TSLP serum levels." (PMID 20174635, 2010).
ependymoma (1 paper, 2021). A WHO grade II, slow growing tumor of children and young adults, usually located intraventricularly. "By elucidating core transcriptional regulatory circuitries from the set of gained enhancers, we identified several key TFs, including RXRA, NFE2L2, IRF2, RELA, etc., involved in cell growth and migration, some of which were also revealed to have tumor-promoting functions in ependymoma and RCC25,26." (PMID 34294701, 2021).
experimental autoimmune encephalomyelitis (1 paper, 2025). An autoimmune demyelinating disease of the central nervous system that is produced experimentally in animals by the injection of homogenized brain or spinal cord in Freund's adjuvant. "CD16+ monocytes showed downregulation of select transcription factor genes (RXRA, IKZF1, KLF4, IRF4) and CD81, a marker that facilitates monocytes homing to the CNS in experimental autoimmune encephalomyelitis (EAE)." (PMID 40067358, 2025).
glioblastoma (1 paper, 2025). The most malignant astrocytic tumor (WHO grade IV). "FABP7 activates nuclear receptor RXRα to drive the migration of glioblastoma stem cell-like cells (GSC), inducing tumor cell chemoresistance and recurrence." (PMID 40717587, 2025). "FABP7 is highly expressed in glioblastoma tumor stem cells (GSCs) and drives the migration and infiltration of glioblastoma cells through the RXRα signaling pathway." (PMID 40717587, 2025). "FABP7 drives lipid droplet formation and radioresistance in glioblastoma stem cells through the RXRα signaling pathway." (PMID 40717587, 2025).
HCMV infection (1 paper, 2022). "Since the VDR employs its functions mostly as a heterodimeric holoenzyme with RXRα, we also analyzed RXRα expression in the context of HCMV infection." (PMID 36146811, 2022).
head and neck cancer (1 paper, 2021). A primary or metastatic malignant neoplasm affecting the head and neck. "Additionally, in head and neck cancer stem cells cisplatin resistance can be modulated by RXRα through CTR1 expression." (PMID 33469038, 2021).
Hyperinsulinemia (1 paper, 2017). An increased concentration of insulin in the blood. "However, increased visceral adipose mass and hyperinsulinemia are not expected effects of PPARγ and RXRα activation." (PMID 28824431, 2017).
hyperthyroidism (1 paper, 2024). Overactivity of the thyroid gland resulting in overproduction of thyroid hormone and increased metabolic rate. "Thus, it seems possible that similar mechanisms (T3 → TRβ/RXRα → HLF → HIF-1α → EPO and T3 → SHH → BMP-4 → BFU-E) may lead to increased erythropoiesis in human and feline hyperthyroidism and may explain the presence of erythrocytosis observed in this disease." (PMID 39518858, 2024).
hypertriglyceridemia (1 paper, 2023). A laboratory test result indicating elevated triglyceride concentration in the blood. "The degree to which the agonists of RXRA cause acute hypertriglyceridemia differs by the duration of agonist exposure." (PMID 36674699, 2023).
Immunodeficiency (1 paper, 2017). Failure of the immune system to protect the body adequately from infection, due to the absence or insufficiency of some component process or substance. "The NRs in the autoimmune/immunodeficiency disease group include PPARG (systemic lupus erythematosus), RORC (immunodeficiency), and RXRA (systemic lupus erythematosus)." (PMID 29065888, 2017).
Infertility (1 paper, 2022). "RXRA was detected in Sertoli cells and germ cells within the testes, with under-expression found in infertile men." (PMID 35585482, 2022). "Similarly, depletion of RXRA leads to infertility in male mice indicating a crucial role of RXRA for healthy sperm development." (PMID 35585482, 2022).
intracerebral hemorrhage (1 paper, 2024). A cerebrovascular disorder characterized by bleeding into one or both cerebral hemispheres including the basal ganglia and the cerebral cortex. "Egr-1 increases RXRa acetylation by modulating p300, thereby exacerbating cerebral injury in a rat model of intracerebral hemorrhage and dysfunction in BMECs via the STAT3/NF-κB pathway." (PMID 38233877, 2024).
ischemic stroke (1 paper, 2014). A stroke disorder caused by obstruction of blood flow to the brain, due to thrombotic (local blood clot formation) or embolic (due to a blood clot or other material traveling from another site) event. "A number of interconnected pathways previously associated with ischemic stroke were over-represented in females, including TLR (Toll-like receptor), HMGB1, TREM1, PPARα/RXRα, Hypoxia, Renin-Angiotensin, Mitochondrial Dysfunction, Glucocorticoid receptor and cytokine signaling pathways." (PMID 25036109, 2014).
lymph node metastasis (1 paper, 2020). "In conclusion, our study showed that increased RXRα expression was associated with reduced migration, invasion and degree of EMT in metastatic colorectal carcinoma and decreased RXRα expression was associated with high lymph node metastasis." (PMID 33128348, 2020). "In addition, we showed that RXRα expression was related to lymph node metastasis." (PMID 33128348, 2020). "Therefore, the lack of RXRα might be a risk factor for lymph node metastasis." (PMID 33128348, 2020).
metastasis (1 paper, 2020). The spread or migration of cancer cells from one part of the body (where they first appeared) to another. "There was a moderate negative correlation only between RXRα expression and N stage which represents the level of lymph node metastasis." (PMID 33128348, 2020).
Miscarriage (1 paper, 2013). A pregnancy that ends at a stage in which the fetus is incapable of surviving on its own, defined as the spontaneous loss of a fetus before the 22th week of pregnancy. "We correlated the IRS score of the nuclear receptor LXR, PPARγ, and RXRα in all miscarriage patients and all control trophoblast." (PMID 23690759, 2013). "For nuclear receptor, RXRα and PPARγ we also found an upregulation in spontaneous miscarriage." (PMID 23690759, 2013). "To conclude, our data show that LXR expression is decreased in miscarriage and this is attended by changes in correlation changes of LXR with its heterodimer partners RXRα and PPARγ, possibly as a result of oxidative stress or proinflammatory processes." (PMID 23690759, 2013).
mucinous carcinomas (1 paper, 2022). "Analysis of the correlation between RXRα expression and histopathological parameters revealed: median IRS in serous specimens was 2 (SD ± 0.147) compared to a median IRS of 3.5 in mucinous carcinomas (SD ± 0.499; p = 0.424)." (PMID 34870752, 2022).
myeloma (1 paper, 2014). "We also demonstrate that over-expression of ALDH1A1 in myeloma leads to elevated NEK2 levels, using a mechanism that includes 9-cis retinoic acid-dependent RXRα signaling." (PMID 25230277, 2014). "The activation of NEK2 in myeloma cells relied on the ALDH1A1-dependent generation of the retinoid X receptor α (RXRα) ligand, 9-cis retinoic acid (9CRA) – not the retinoic acid receptor α (RARα) ligand, all-trans retinoic acid (ATRA)." (PMID 25230277, 2014).
nephrolithiasis (1 paper, 2025). The presence of a calculus in the pelvis of the kidney; this is most often composed of mineral salts and proteins. "Comprehensive epigenomic and transcriptomic profiling revealed a dynamic enhancer landscape and gene expression program associated with nephrolithiasis, highlighting RXRα as a central transcription factor in this regulatory network." (PMID 40091688, 2025). "Therefore, activating RXRα with Bex can reshape enhancers and regulate the expression of many nephrolithiasis‐associated genes." (PMID 40091688, 2025). "Moreover, a correlation analysis revealed an inverse association between RXRα expression levels and the size of kidney stones." (PMID 40091688, 2025). "Next, we proceeded to examine the changes in enhancer activation markers, specifically H3K27ac and H3K4me1, on those Bex‐inhibited/RXRα‐bound nephrolithiasis‐promoting genes after Bex treatment." (PMID 40091688, 2025). "Mechanistically, under normal circumstances, RXRα inhibited nephrolithiasis‐promoting genes by recruiting the HDAC3/SMART complex to repress enhancer activity." (PMID 40091688, 2025). "Yet, with the progression of CaOx crystal deposition, RXRα expression decreased, leading to enhancer activation and subsequent upregulation of nephrolithiasis‐promoting genes." (PMID 40091688, 2025). "Integrating these ChIP‐seq data with RNA‐seq data, we identified 1082 nephrolithiasis‐promoting genes as Bex‐inhibited/RXRα‐bound genes." (PMID 40091688, 2025). "Our study shows that activation of RXRα can effectively reduce CaOx crystal deposition by downregulating genes that facilitate nephrolithiasis." (PMID 40091688, 2025). "Additionally, we found that RXRα recruited the SMART/HDAC3 co‐repressor complex to inhibit the transcription of these nephrolithiasis‐promoting genes." (PMID 40091688, 2025). "Furthermore, experiments with Rxrα knockout mice suggest that the effectiveness of Bex in delaying nephrolithiasis progression depended on RXRα." (PMID 40091688, 2025). "Tubular‐specific deletion of RXRα increased intrarenal CaOx crystal deposition, while its activation with Bexarotene suppressed this process by reprogramming enhancer profiles and downregulating nephrolithiasis‐promoting genes." (PMID 40091688, 2025). "To investigate whether RXRα recruits SMRT and HDAC3, we conducted ChIP‐qPCR experiments to assess the binding of SMRT, and HDAC3 on the representative Bex‐inhibited/RXRα‐bound nephrolithiasis‐promoting genes in TECs." (PMID 40091688, 2025). "Moreover, our data, which correlate human RXRα expression levels with crystal occurrence and size, underscore the clinical relevance of our findings and highlight the potential for RXRα modulation as a promising therapeutic avenue in managing nephrolithiasis." (PMID 40091688, 2025). "Likewise, we observed a substantial reduction in RXRα protein levels within the renal tubular cells of patients with nephrolithiasis as compared to controls." (PMID 40091688, 2025). "Therefore, our subsequent analysis concentrates on exploring how the activation of RXRα by Bex inhibits the expression of these nephrolithiasis‐promoting genes." (PMID 40091688, 2025). "CaOx treatment reduced RXRα expression and derepressed SMART/HDAC3 suppressors, leading to enhancer activation and increased expression of those genes that promote nephrolithiasis." (PMID 40091688, 2025).
oral cancer (1 paper, 2022). "Bexarotene might be effective in patients with high risk scores, and its anti-HNSCC efficacy was evidenced by targeting the PPARγ/RXRα heterodimer oral cancer preclinical test." (PMID 36105083, 2022).
periapical granuloma (1 paper, 2021). Chronic nonsuppurative inflammation of periapical tissue resulting from irritation following pulp disease or endodontic treatment. "MCODE-1 with the highest significance for nuclear receptor transcription pathway and the highest PPI in periapical granuloma was between RXRA, PPARG, ESR1, ESRRA, and NR0B1 proteins." (PMID 34539639, 2021).
renal fibrosis (1 paper, 2022). A final common manifestation of a wide variety of chronic kidney diseases characterized by glomerulosclerosis and tubulointerstitial fibrosis. "Next, we asked whether activating RXRα can promote renal repair and ameliorate renal fibrosis after SI." (PMID 36443310, 2022).
rosacea (1 paper, 2025). A chronic erythematous skin disorder that affects the face. "ROC curve analysis further validated the diagnostic potential of these genes, with XDH exhibiting an AUC of 0.967, RXRA with 0.916, and BCL2 with 0.693, highlighting XDH and RXRA as robust biomarkers for rosacea." (PMID 40474977, 2025). "Notably, XDH expression was significantly upregulated in rosacea lesions, whereas BCL2 and RXRA were downregulated compared to healthy controls." (PMID 40474977, 2025). "Analysis of the GSE65914 dataset showed that XDH was upregulated in rosacea lesions, while BCL2 and RXRA were downregulated, with no significant expression changes of the other genes." (PMID 40474977, 2025).
thymoma (1 paper, 2022). A neoplasm arising from the epithelial cells of the thymus.
vitamin A deficiency (1 paper, 2021). Deficiency of vitamin A due to malnutrition, malabsorption, or dietary lack. "Based on the consequences of systemic vitamin A deficiency and reduced RXRα signaling, there appears to be a retinoid axis on the ocular surface that is required for maintaining a healthy, well lubricated ocular surface and suppressing innate inflammation." (PMID 33499199, 2021).
vitamin D deficiency (1 paper, 2022). A nutritional condition produced by a deficiency of VITAMIN D in the diet, insufficient production of vitamin D in the skin, inadequate absorption of vitamin D from the diet, or abnormal conversion of vitamin D to its bioactive metabolites. "The effect of early life vitamin D deficiency on the DNA methylation of Runx2, Osterix, VDR, and RXRA, genes known to play essential roles in bone formation, was assessed." (PMID 35619053, 2022).